HLA-DMA (major histocompatibility complex, class II, DM alpha)
Description:
Plays a critical role in catalyzing the release of class II-associated invariant chain peptide (CLIP) from newly synthesized MHC class II molecules and freeing the peptide binding site for acquisition of antigenic peptides. In B-cells, the interaction between HLA-DM and MHC class II molecules is regulated by HLA-DO.
Synonyms: DMA; RING6; D6S222E; HLADM
Tractability: Antibody: UniProt predicts a signal peptide or a membrane-spanning region. PROTAC: ubiquitination databases record sites on it.
Gene: Protein-coding gene on chromosome 6 (32,948,613 to 32,969,094, reverse strand). Ensembl gene ENSG00000204257.
Subcellular location: Late endosome membrane; Lysosome membrane
Subcellular location (Human Protein Atlas): Vesicles
Pathways (Reactome):
Immune System: MHC class II antigen presentation
Gene Ontology:
Molecular function: MHC class II protein complex binding; protein binding; peptide antigen binding
Biological process: peptide antigen assembly with MHC class II protein complex; antigen processing and presentation of exogenous peptide antigen via MHC class II; positive regulation of immune response; positive regulation of T cell activation; antigen processing and presentation; immune response
Cellular component: cell surface; late endosome membrane; lysosomal membrane; membrane; MHC class II protein complex
Genetic constraint (gnomAD): Loss-of-function variants: 19 observed, 28.86 expected, observed/expected ratio (o/e) 0.66, 90% interval 0.46 to 0.97. The upper end of that interval is the gene's LOEUF score, 0.97, which puts it in group 4 of 6, group 1 being the genes least tolerant of losing a copy. Missense variants: 241 observed, 338.84 expected, observed/expected ratio (o/e) 0.71, 90% interval 0.64 to 0.79. Synonymous variants: 111 observed, 134.19 expected, observed/expected ratio (o/e) 0.83, 90% interval 0.71 to 0.97.
Homologues: Orthologues: chimpanzee MAMU-DMA (88% identical), dog HLA-DMA (79% identical), pig SLA-DMA (79% identical), mouse H2-DMa (76% identical), guinea pig HLA-DMA (75% identical), rat RT1-DMa (70% identical), rabbit HLA-DMA (69% identical), tropical clawed frog mhc2-dma (31% identical). Paralogues in human: HLA-DPA1 (26% identical), HLA-DOA (25% identical), HLA-DQA2 (25% identical), HLA-DQA1 (24% identical), HLA-DRA (21% identical), HLA-DMB (20% identical), HLA-DRB1 (19% identical), HLA-DPB1 (18% identical), HLA-DRB5 (18% identical), HLA-DOB (17% identical), HLA-DQB2 (16% identical), HLA-DQB1 (16% identical), and 1 more.
Diseases named in the same sentence as HLA-DMA in open-access papers:
HLA-DMA is named in the same sentence as 72 diseases in open-access papers, as found by Europe PMC text mining. Sharing a sentence is not in itself a finding about the gene and the disease. The quoted sentences say what the papers report.
rheumatoid arthritis (7 papers, 2018 to 2025). A chronic, systemic autoimmune disorder characterized by inflammation in the synovial membranes and articular surfaces. "Some of these novel risk genes such as DDAH2 and HLA-DMA have been reported to be associated with the autoimmune diseases, including type I diabetes, rheumatoid arthritis, and systemic lupus erythematosus." (PMID 34872583, 2021).
breast carcinoma (6 papers, 2013 to 2025). "Although HLA-DMA was previously associated with breast cancer, it is also known to have a role in cancer progression and resistance to drugs." (PMID 36945359, 2023).
Sepsis (6 papers, 2021 to 2025). Sepsis is defined as life-threatening organ dysfunction caused by a dysregulated host response to infection. "Through searching the sepsis-related publication of the key genes, CCR7, CXCR3, FYN, CEACAM1, CD81, AMPH, HLA-DMA, and G protein-coupled receptors (GPR18) were considered to be key genes." (PMID 34484417, 2021). "Similar to T cells and NK cells in sepsis, both naïve and switched resting B cell populations display significant decreases in the expression of several MHC-class II genes, including HLA-DRA, HLA-DRB1, HLA-DMA and HLA-DPA1." (PMID 41208955, 2025). "CXCR3, CCR7, HLA-DMA, and GPR18 might be correlated with the sepsis mechanism." (PMID 34484417, 2021). "CXCR3, CCR7, HLA-DMA, and GPR18 might participate in the mechanism of CAP with sepsis." (PMID 34484417, 2021). "Moreover, cytokine IL-10 inhibits the expression of Class II major histocompatibility complex (MHC) proteins (HLA-DR, HLA-DMA, and HLA-DMB) on the surface of macrophages and monocytes, which in addition to TGF-β, suppresses T-cell proliferation, contributing to immunosuppression in sepsis." (PMID 38235139, 2023).
systemic lupus erythematosus (6 papers, 2016 to 2023). An autoimmune multi-organ disease typically associated with vasculopathy and autoantibody production. "By KEGG pathway analysis, six genes, i.e., C4A, C4B, FCGR2A, HLA-DMA, HLA-DRA, and HLA-DRB1, were enriched as the top 2 significant results in the pathways of Staphylococcus aureus infection (KEGG term hsa05322, FDR = 1.42E−05) and systemic lupus erythematosus (KEGG term hsa05150, FDR = 2.00E−04)." (PMID 34804021, 2021).
COVID-19 (4 papers, 2020 to 2023). A disease caused by infection with severe acute respiratory syndrome coronavirus 2. "In contrast, downregulation of genes encoding HLA class 2 (HLA-DRA, HLA-DPA1, HLA-DMA, DYNLL1) was found in COVID-19 ECs which was further confirmed by GSEA analysis." (PMID 37029220, 2023). "Further, we investigated the expression of MHC class II molecules (MHCII) and Fc receptors (FcRs) and found that they were broadly upregulated in APCs in lungs of mild COVID-19 patients, with a MHCII subset (HLA-DRA, HLA-DMB, HLA-DRB1, HLA-DPB1, HLA-DQB1, HLA-DMA) were downregulated." (PMID 34502134, 2021). "Regarding the downregulated geneset, MHC II molecules, including HLA-DQA1, HLD-DRA, HLA-DRB1, HLA-DMB, HLA-DMA, etc., and cytokine/chemokine genes, including IL1B, TNF, CCL3, CCL4, and CXCL8 were expressed at lower levels in COVID-19 patients, especially those with severe diseases." (PMID 33101705, 2020).
ovarian carcinoma (4 papers, 2020 to 2024). A malignant neoplasm originating from the surface ovarian epithelium. "Major Histocompatibility Complex molecule also close to CX3XR1 expression in epithelial ovarian cancer, like HLA-DMA (R = 0.49, P < 2.2e−16) and HLA-DPA1 (R = 0.473, P < 2.2e−16)." (PMID 38241595, 2024). "MSLN was positively correlated with immunosuppressive genes in ovarian cancer, such as LGALS9, CD276, TMIGD2, CD200, TNFRSF14, and human leukocyte antigen (HLA)-related families including HLA-DRA, HLA-DRB1, HLA-DPA1, HLA-DMA, HLA-E, etc.." (PMID 35692779, 2022). "Besides, MHC molecules, including HLA-B (cor = 0.365, p = 5.69e-11), HLA-DMA (cor = 0.413, p = 7.02e-14), HLA-DPA1 (cor = 0.475, p = 2.03e-18), HLA-DQA1 (cor = 0.467, p = 8.07e-18), and HLA-E (cor = 0.447, p = 2.6e-16), were significantly correlated with the expression of SUCNR1 in ovarian cancer." (PMID 33062639, 2020).
glioma (3 papers, 2020 to 2025). A benign or malignant brain and spinal cord tumor that arises from glial cells (astrocytes, oligodendrocytes, ependymal cells). "Furthermore, the correlation analysis indicated that the expression of IFI30, an acknowledged biomarker in glioma, was positively correlated with HLA-DMA, P4HB and RCN1." (PMID 35436915, 2022).
bladder cancer (2 papers, 2023). "Additionally, three proteins were under-expressed in samples of bladder cancer patients in this study: human leukocyte antigen class II histocompatibility antigen alpha chain (HLA-DMA), Na(+)/H(+) exchange regulatory cofactor 1 (NHE-RF1, SLC9A3R1) and uncharacterized protein C11orf52 (C11orf52)." (PMID 37371512, 2023).
colon adenocarcinoma (2 papers, 2024). "Moreover, among 19 Hub-MHCsig, HLA-DMA, HLA-DMB, and HLA-DOA were positively correlated with microsatellite instability in colon adenocarcinoma, while TAP2, TAP1, and HLA-F were negatively correlated with microsatellite instability in testicular germ cell tumors." (PMID 38714579, 2024).
parasite infection (2 papers, 2021 to 2024). "Thus, POR is indirectly responsible for regulation of expression of CIITA along with the molecules of MHC II group such as CD74, HLADQA1, HLADMA, HLADQB1 and HLADRB5 previously identified as genes responsible for inhibition of parasite infection." (PMID 34946170, 2021).
autism (1 paper, 2020). Persistent deficits in social interaction and communication and interaction as well as a markedly restricted repertoire of activity and interest as well as repetitive patterns of behavior. "These previous studies support our findings suggesting that the HLA-DMA gene in the class II region might be associated with autism." (PMID 33384710, 2020).
Burkitt lymphoma (1 paper, 2006). A rare form of malignant mature B-cell non-Hodgkin lymphoma. "The binding of Myc to HLA-DMA has been demonstrated in a study of the regulatory role for c-Myc in Burkitt's lymphoma cells." (PMID 16670008, 2006).
cytomegalovirus infection (1 paper, 2023). A herpesvirus infection caused by Cytomegalovirus. "Modulation of the MHC II-mediated cellular immune response has been also described for human cytomegalovirus infection, where the viral protein pUS2 destroys HLA-DMA and -DRA to prevent recognition by CD4 + T cells." (PMID 37604847, 2023).
endothelial dysfunction (1 paper, 2025). In vascular diseases, endothelial dysfunction is a systemic pathological state of the endothelium (the inner lining of blood vessels) and can be broadly defined as an imbalance between vasodilating and vasoconstricting substances produced by (or acting on) the endothelium. "These DORs were located at promoters of genes including CD74, IFI27, HLA-DMA, CASP8 and NOX4, which are associated with antigen presentation, inflammation and endothelial dysfunction." (PMID 41085167, 2025).
head and neck squamous cell carcinoma (1 paper, 2023). A squamous cell carcinoma that arises from any of the following anatomic sites: lip and oral cavity, nasal cavity, paranasal sinuses, pharynx, larynx, and salivary glands. "The downregulation of HLA-DMA has also been previously seen in head and neck squamous cell carcinoma." (PMID 37371512, 2023).
lung adenocarcinoma (1 paper, 2024). A carcinoma that arises from the lung and is characterized by the presence of malignant glandular epithelial cells. "Recently, it was demonstrated that HLA-DMA, identified as a crucial TME-related gene in lung adenocarcinoma (LUAD), correlates positively with survival and may serve as a potential biomarker for immune infiltration and response to immunotherapy." (PMID 38256356, 2024).
osteosarcoma (1 paper, 2024). A usually aggressive malignant bone-forming mesenchymal neoplasm, predominantly affecting adolescents and young adults. "The prognostic biomarkers C1QA, CD74, and HLA-DMA for pediatric metastatic osteosarcoma were identified using RNA-sequencing data (level 3) associated with clinical information from the TARGET-osteosarcoma dataset." (PMID 38256356, 2024). "In conclusion, our research identified three novel metastasis-related DEGs associated with the survival of pediatric osteosarcoma patients: C1QA, CD74, and HLA-DMA." (PMID 38256356, 2024). "The present study delves into the intricate roles of C1QA, CD74, and HLA-DMA, exploring their interactions within the tumor microenvironment and their implications for the immunotherapy response, thereby providing new insights into the treatment of pediatric osteosarcoma." (PMID 38256356, 2024).
periodontitis (1 paper, 2025). An acute or chronic inflammatory process that affects the tissues that surround and support the teeth. "After integrating DNA methylation with transcriptome profiles, GRASP, HLA-DMB, HLA-DMA, CAB39, NCOA2 and TLE4 were identified as candidate genes in periodontitis PMNs." (PMID 40267082, 2025). "Our results showed that DNMT3B was significantly negatively correlated with GRASP, HLA-DMB, HLA-DMA, CAB39, and TLE4, implying the predominant role of DNMT3B in periodontitis." (PMID 40267082, 2025).
renal agenesis (1 paper, 2019). Renal agenesis (RA) is a form of renal tract malformation characterized by the complete absence of development of one or both kidneys (unilateral RA or bilateral RA respectively), accompanied by absent ureter(s). "Other interesting candidate adaptive genes include HLA-DMA involved in immunity, FRAS1 associated with renal agenesis, SREBF2 related to female reproduction and DISC1 associated with response to the ultraviolet (UV) exposure." (PMID 34691999, 2019).
sarcoma (1 paper, 2014). A usually aggressive malignant neoplasm of the soft tissue or bone. "All but one of these genes (HLA-DMA) have reported somatic mutations in the COSMIC database, but none of our SNV are shared and none of these genes have reported mutations in sarcomas." (PMID 24505276, 2014).
septic shock (1 paper, 2013). Shock caused by infection; frequently caused by gram negative bacteria, although some cases have been caused by other bacteria, viruses, fungi, and protozoa; characterized by fever, chills, tachycardia, tachypnea, and hypotension. "In a cohort of 93 septic shock patients alive three days after shock, mHLA-DR was measured by flow cytometry and CD74, HLA-DRA, HLA-DMA, HLA-DMB and CIITA mRNA levels were evaluated in whole blood by qRT-PCR." (PMID 24321376, 2013).
viral infection (1 paper, 2018). "Based on known association between acute viral infection and the MHC region, it is reasonable to infer that more transcription of HLA‐DMA and HLA‐DMB (class II alleles) would correlate with higher anti‐CHIKV antibody titers, since they are involved in both the adaptive and humoral responses." (PMID 30150281, 2018).
tumor (36 papers, 2003 to 2025). "Subsequently, we collected several clinical GBM tumor tissues and detected the expression levels of HLA-DMA, P4HB and RCN1 in GBM via qRT-PCR and IHC assays." (PMID 35436915, 2022). "CD74, GIMAP4, HCST, and HLA-DMA not only showed good clinical phenotype correlation but also correlated with M2 type macrophages, tumor purity, and immune score." (PMID 33854546, 2021). "In fact, studies have reported that IFI30 and HLA-DMA could be related to immune response process which play tumor-regulatory roles in GBM." (PMID 35436915, 2022). "Interestingly, our study showed strong association of five HLA genes (including HLA-DMA, HLA-DMB, HLA-DOA, HLA-DRB6 and HLA-E) with delayed tumor recurrence in both cohorts." (PMID 34834481, 2021). "Furthermore, a number of interferon (IFN) response genes (BST2, CD74, HLA-DMA, HLA-DPB1, HLA-DQB1, HLA-DRA, HLA-DRB1, and IRF8) were upregulated in C10 compared to the other clusters, whereas genes associated with tumor suppression and apoptosis (TFF1 and TFF2) were downregulated." (PMID 37370788, 2023). "The top 100 genes found to be co-expressed with CD74 were examined using GEPIA2.0, finding that the top five genes (HLA-DMA, HLA-DPA1, HLA-DPB1, HLA-DRA, and HLA-DRB1) were highly correlated with CD74 in most tumor types." (PMID 38582956, 2024). "Through transcriptional trajectory analysis, we discovered a specific cluster of tumour cells in LSCC with COPD that exhibited high expression levels of MHC II‐related genes, including CD74, HLA‐DRA and HLA‐DMA." (PMID 39113235, 2024). "Additionally, ENHO was positively co-expressed with MHC class II presentation genes (including HLA-DMA, HLA-DOA, HLA-DPA1, HLA-DPB1, and HLA-DRB1), supporting its role in promoting anti-tumor immunity." (PMID 40647442, 2025). "It is worth noting that the interaction between HLA‐II molecules (such as HLA‐DRA, HLA‐DRB1, HLA‐DRB5, HLA‐DQB1, HLA‐DPB1, HLA‐DPA1, HLA‐DMB and HLA‐DMA) and the receptor CD4 was exclusively detected in the cell communication between malignant cells from single‐primary tumours and Tregs." (PMID 39601163, 2024). "Human MHC class II molecules (HLA-DMB, HLA-DMA, HLA-DRA, HLA-DOA) in the top 30 DMRs, which could attract inflammatory tumour-specific CD4+ T cells and dampen CD8+ T cell antitumour reactivity, were found to be hypomethylated in all CLL patients in our study." (PMID 36712882, 2022). "Notably, some genes related to exhaustion were also overexpressed in tumor‐infiltrating Tregs including TYMS, KIAA0101, CXCL13, CD27, HLA‐DQB1, HLA‐DMA, ENTPD1, CD200, DUSP4, and ZBED2." (PMID 32659053, 2020). "Moreover, we observed a reduced expression of HLA class II molecules (CD74, HLA-DRA, HLA-DRB1, HLA-DMA), which might affect the number and function of CD4+ T lymphocytes in the tumor microenvironment." (PMID 36153593, 2022). "Other proteins, including HLA-A, HLA-DMA, HLA-DQA1, HLA-DQB1, HLA-DRA, HLA-DRB1, and HLA-DRB5, were not reported on tumor–host immunological interactions, which indicated the proteins need further studies to testify them as novel OC biomarkers for tumor immunology." (PMID 31258820, 2019). "However, analysis of single‐cell RNA‐sequencing (RNA‐seq) of GB patient tumors revealed that tumor cells do not express CIITA nor genes encoding for MHC‐II antigen processing (CD74, HLA‐DMA, HLA‐DOA) and presentation (HLA‐DQA1, HLA‐DQB1, HLA‐DRA, HLA‐DRB1, HLA‐DRB5)." (PMID 39535369, 2025). "Furthermore, the HLA-DMA and HLA-DMB genes are expressed at high relative levels, similar to those for CDH1 (epithelial cells) and CD68 (macrophages), suggesting that they may be expressed by these cell types within the tumor." (PMID 36497170, 2022).
cancer (10 papers, 2017 to 2024). A tumor composed of atypical neoplastic, often pleomorphic cells that invade other tissues. "We noticed that some MHC class II genes (HLA-DMA, HLA-DPA1, HLA-DPB1, HLA-DRA, HLA-DRB1) were significantly down-regulated in cancer cells with relatively poor differentiation states compared with those with better differentiation states for 5/6 mGC patients." (PMID 37347037, 2023).
kidney disease (1 paper, 2021). "Our findings indicate that a high expression of different co-DEGs was correlated with a low glomerular filtration rate in kidney disease samples (IL10RA, HLA-DPA1, r = −0.490, p < 0.001; IRF8, HLA-DRA, r = −0.500, p < 0.001; HLA-DPB1, r = −0.510, p < 0.001; HLA-DMA, r = −0.480, p < 0.001)." (PMID 34692653, 2021).
neurological disorders (1 paper, 2022). "Interestingly, several genes encoded in the HLA locus, which has been implicated in SCZ and other psychiatric and neurological disorders, were picked up by our inference downstream of the identified transcription factors (HLA-DOA, HLA-DOB, HLA-DRB1, HLA-DMA, and BRD2)." (PMID 36344995, 2022).
HLA-DMA also shares sentences with these, for which no sentence is quoted: type 1 diabetes (6 papers); autoimmune disease (4); Autoimmunity (3); leukemia (3); melanoma (3); glioblastoma (2); Hodgkins lymphoma (2); infection (2); lymphoma (2); schizophrenia (2); Stroke (2); acute graft versus host disease (1); adenocarcinoma (1); Allergy (1); ankylosing spondylitis (1); asthma (1); autoimmune thyroid disease (1); B cell lymphomas (1); bare lymphocyte syndrome (1); cardiovascular diseases (1); cervical tumor (1); chronic hepatitis C (1); coeliac disease (1); cutaneous melanoma (1); dementia (1); diabetes (1); diffuse large B-cell lymphoma (1); diseases of the immune system (1); Epstein-Barr virus infection (1); gastrointestinal disease (1).
A further 16 diseases each share a sentence with HLA-DMA in 1 paper.